CAT (catalase)
Diseases named in the same sentence as CAT in open-access papers (continued):
Sharing a sentence is not in itself a finding about the gene and the disease.
infection (continued). "Following the infection treatment, CAT activity of ‘CDR-1’ plants increased at 15 dpi, but no such difference was evident between the treatment with inoculation and wounded control groups in ‘Gisela 6’." (PMID 33183241, 2020). "A potential player in cell resilience may be the levels of peroxisome-related enzymes, CAT and SOD, which seem to differ based on cell type (i.e., myeloid and T-cell) and infection status." (PMID 32823598, 2020). "But, at 36 h and 48 h when compared to control, there were not much difference observed in the level of CAT activity in sodium alginate pretreated leaves followed by pathogen infection." (PMID 31568481, 2019). "Results showed that ZT significantly increased SOD and CAT activities in salt-stressed seedlings, irrespective of pathogen infection." (PMID 31877189, 2019). "Catalase activity was higher in fish fed GRA diet within the placebo groups (p = 0.002), and no statistical differences were detected between diets in Phdp infected groups or the interaction of both diet and infection." (PMID 31695116, 2019). "In addition, LL-5 cells expressed high levels of iNOS at 12 h post-infection with wMel and at 24 h to wMelPop-CLA, and low levels of Catalase expression at 48 for wMel and 72 h for wMelPop-CLA post-challenges." (PMID 30646951, 2019). "We further detected whether CAT is differentially regulated by endogenous and exogenous ABA under PstDC3000 infection." (PMID 31126160, 2019). "In addition, the activities of catalase (CAT), peroxidase (POD), and the malondialdehyde (MDA) content were also largely reduced after pathogen infection, with the root activity being higher than that of the control." (PMID 30337932, 2018). "In addition, anti-oxidant genes responded in differential patterns, in which CAT1 (catalase) and POD1 (peroxidase) were strongly induced at early stage upon pathogen infection in the priming group." (PMID 30444911, 2018). "In addition, indole priming triggered anti-oxidant gene expression drastically, particularly CAT and POD for H2O2 scavenging, upon pathogen infection." (PMID 30444911, 2018). "For example, in response to infection with Botrytis cinerea, leaves of ivy pelargonium (Pelargonium peltatum), showed a strong nitric oxide (NO) burst and H2O2 accumulation to arrest disease progression through NO-dependent reversible inhibition of catalase." (PMID 29466404, 2018). "On the other hand, addition of catalase reduced the rate of survival of the WT and Wr strains at 1 h after infection, whereas there was no significant change in survival rate of the KO strain at that time point." (PMID 28222125, 2017). "On the other hand, treatment of cultures with catalase did not interfere with Col1.7G2 intracellular growth, since the number of intracellular parasites along the course of infection was very similar in both treated and catalase treated conditions." (PMID 28832582, 2017). "When infected with Dengue 4 and Zika virus, catalase-silenced mosquitoes showed no alteration in infection intensity (number of plaque forming units/midgut) 7 days after the infectious meal." (PMID 28379952, 2017). "Infection by P. aeruginosa, and subsequent secretion of PCN, has been shown to have a dramatic effect on the cellular protective mechanisms of the enzymes superoxide dismutase (SOD), catalase (CAT), and glutathione peroxidise (GSH-Px)." (PMID 27517959, 2016). "Catalase can protect catalase-producing bacteria from environmental H2O2 and prolong infection." (PMID 25880161, 2015). "B2-induced oxidative stress can up-regulate the antioxidative enzymes, Mn SOD, catalase, and Nrf2, and RGNNV-induced H2O2 signaling may modulate viral replication in the early and middle stages (24–48 h post-infection)." (PMID 25008790, 2014). "However, when enzyme activity was measured in the midgut, both catalase and SOD showed reduced activity after infection." (PMID 23441231, 2013).
infection (continued). "Surprisingly, no bifunctional catalase-peroxidase was identified although for numerous pathogens, these enzymes have already been shown to be involved in the infection of macrophages." (PMID 22879963, 2012). "Furthermore, both antioxidants diphenyliodonium and N-acetylcysteine or overexpression of zebrafish catalase in GF-1 cells also reduced ROS production and protected cells for enhancing host survival rate due to RGNNV infection." (PMID 21991373, 2011). "Beside this, during infection, H2O2 produced by dismutation of superoxide anion may have been efficiently converted to O2 by CAT and the enzyme activities showed a marked reduction." (PMID 21785683, 2011). "On the other hand, RGNNV infection did apparently upregulate Nrf2, Cu/Zn SOD and catalase at 48 h pi, which may help to restore ROS homeostasis." (PMID 21991373, 2011). "Under these conditions, the EBL cells showed dramatic morphological changes 24 h post infection as in the absence of catalase." (PMID 17439646, 2007). "No significant increase in the catalase activity in NeRCaMs was observed after control infection compared to untreated cells (blank, P<0.485) up to 72 h postinfection." (PMID 14647150, 2003). "The results confirmed that the infection involved a free-radical-mediated damage mechanism: TBARS levels increased almost 3-fold, the AOC decreased more than 4-fold, SOD was increased nearly 5-fold, CAT was increased by 1.4 times, and GRA was suppressed by 2.5 times." (PMID 40332548, 2025). "Thus, the ABA treatment of the Om35 plants did not affect CAT activity during infection compared to the infected, untreated plants." (PMID 39942917, 2025). "Similarly, the activity of the most abundant peroxisomal enzyme, catalase, did not change after infection, similar to proteomic analysis." (PMID 39695325, 2025). "In the absence of infection, CAT helps maintain neuroglial cells." (PMID 40332798, 2025). "After BoDV1 infection of TNFTg mice, peroxisomal and catalase abundances did not change in neuronal cells from transgenic brain areas, suggesting that mild chronic TNF pre-sensitization of neurons in vivo counteracted changes in peroxisomal and catalase abundance after BoDV1 infection." (PMID 38339126, 2024). "In general, the higher SOD, CAT, and GR activities for IR-stimulus-sprayed plants attenuated the excessive production of H2O2 and O2●−, and consequently lowered the pool of MDA during infection by B. maydis." (PMID 39795339, 2024). "While infection with the ∆mvfR strain resulted in higher catalase activity than in PA14, it was lower than that displayed by the sham control group, indicating that other functions besides MvfR contribute to the decreased catalase activity in PA14-infected mice." (PMID 38860823, 2024). "Therefore, the antioxidant enzymes, such as CAT and SOD, could be used to maintain a balance of oxidative and antioxidant homeostasis during infection." (PMID 39335239, 2024). "The levels of super oxidase family members, including superoxide dismutase (SOD), catalase (CAT) and peroxidase (POD), were increased at 16 dpi, while JA potentially participated in the resistance response and may only occur during the initial infection period (." (PMID 37303956, 2023). "However, CAT, SOD, and GST activities fluctuated after infection." (PMID 36835731, 2023). "The activities of superoxide dismutase (SOD), peroxidase (POD), catalase (CAT), and the content of malondialdehyde (MDA) in the infected and uninfected maize treatment groups were measured to determine their physiological changes during plant response to the infection." (PMID 36986996, 2023). "Regarding the enzymatic activities, PAL and CAT activities before Cmm infection increased in treatments without beneficial bacteria B. c-A, but after infection, the treatments without beneficial bacteria decreased and treatments with beneficial bacteria increased." (PMID 35406912, 2022).
infection (continued). "These two central regulators of redox homeostasis in plants control detoxification enzymes, such as the catalase CAT2 (Prupe_5G011300, ortholog) and can induce expression of WRKY53 (Prupe_5G117000, ortholog), a transcription factor responding to infection or abiotic stress." (PMID 36275570, 2022). "After inoculation with P. pannosa, the expression levels of NPR1, EDS1, SAG101, PR1, PR5, CAT, chorismate mutase, and PAL increased rapidly, resulting in the rapid synthesis of SA and increasing the acquired resistance of the plant at the early stages of pathogen infection." (PMID 35741765, 2022). "Moreover, the CAT activity of the ‘EverGlade’ seedlings was not significantly difference between the 0th day and 1st day after infection and then decreased significantly, reaching the minimum value on the 9th day, which was 0.2 times that of the 0th day." (PMID 36319971, 2022). "Moreover, in the presence of volatiles, the activity of antioxidant enzymes, i.e., SOD, CAT, POD, and APX, was observed to be enhanced in M. incognita-infested roots, which might reduce the adverse effect of oxidative stress-induced after infection." (PMID 34068779, 2021). "Earlier, we found that the resistance of the T. aestivum to the pathogen S. nodorum was determined by the intensive generation of ROS, mainly H2O2, due to an increase in POD activity and a decrease or absence of an increase in CAT activity in the initial stage of infection." (PMID 34451631, 2021). "In the absence of catalase, ~15% cell death was observed in healthy controls as compared to ~76% for patients with A-T at 8 h, demonstrating an exquisite sensitivity of the A-T cells to infection." (PMID 30796268, 2019). "Thus, based on the result we can hypothesize that sodium alginate pretreatment aid in conferring disease resistance to tomato plants against A. solani by decreasing CAT activity and accumulating higher level of H2O2 at the site of infection." (PMID 31568481, 2019). "We observed by immunohistochemistry that infection with D39 significantly induced the accumulation of PINK1 on the mitochondria in the lung tissue of mice, while both infection with D39ΔspxB and catalase treatment of D39 infection did not increase PINK1-mitochondria interactions." (PMID 30984149, 2019). "Thus, the enhanced activities of SOD, CAT, and APX when O2-. generation rate rise in early stage (0–2 days of storage) of P. longanae-infection might be a defense to reduce contents of ROS." (PMID 30386318, 2018). "Therefore, we speculate that once entered into the intestine, EHEC might use T6SS to secrete catalase KatN to hydrolyze ROS around bacterial cell to form a low ROS level niche and facilitate EHEC population growth, further infection and development of disease." (PMID 28288207, 2017). "In case of simultaneous and alternate inoculation of P. indica and infection of B. cinerea, we found significant increase (P < 0.05) in the GST activity as compared to plant infected with B. cinerea only while significantly (P < 0.05) decreased activity of CAT was observed." (PMID 29051515, 2017). "Likewise, our results suggest that L. migratoria immunity to chlorantraniliprole and M. anisopliae was weakened by increased activities of AA and CHI during the initial post-infection period, whereas the activities of SOD, POD, CAT decreased during the later period." (PMID 27328936, 2016). "After infection, the activity of POD, CAT, and GPX was markedly increased in resistant wheat compared with susceptible wheat, suggesting that these three antioxidant enzymes in inoculated adult plants might play an important role in regulating the levels of ROS." (PMID 26442087, 2015). "At 8 h after exposure to DHV-1, the plasma GSH-Px, SOD, and catalase levels were not significantly different among the four groups, which indicates that the free radical levels were balanced with the enzyme levels during the initial stage of infection." (PMID 25244948, 2014).
infection (continued). "Additionally, catalase (CAT) levels were markedly reduced, while inducible nitric oxide synthase (iNOS), nitric oxide (NO), and the oxidative stress metabolite malondialdehyde (MDA) levels were significantly elevated, indicating pronounced oxidative stress in the intestines following infection." (PMID 40733538, 2025). "In addition to QS, SOD and catalase, which maximize growth under excess OS conditions, PA also produces enzymes such as alkaline protease, elastase and lasA protease, and metabolites such hemolysin, rhamnolipids and phenazines (e.g., pyocyanin (PYO)), to combat host immune cells during infection." (PMID 38929094, 2024). "Furthermore, the presence of high catalase producing M. canis strains in animals without lesions might suggest that the infection was in its early stage and the lesions had not yet appeared as at the time of sampling." (PMID 33809233, 2021). "Therefore, to specifically evaluate the contribution of H2O2 on the infection outcome, we asked whether in vivo neutralization of H2O2 by catalase could similarly increase S. pneumoniae-induced inflammation and whether this in turn could promote bacterial clearance." (PMID 31375698, 2019). "The simultaneous silencing of three genes, catalase, glutathione peroxidase, and thioredoxin as well as the oxidation resistance 1 gene by RNAi apparently favoured the colonization of BME26 cells by A. marginale, suggesting that the antioxidant response might play a role in the control of infection." (PMID 29258559, 2017). "However, we did not observe differences in the transcript levels of catalase between control and transgenic lines after infection with P. infestans(data not shown), suggesting that H2O2 accumulation is mainly caused by potato homologues of PM-localized NADPH oxidases." (PMID 25547733, 2014). "As expected, no CAT activity was detected either in uninfected cells or in cells infected with the virulent strain ZH whereas in agreement with our previously published results, a high level of activity, increasing with time post infection, was observed in C13-infected cells." (PMID 18225953, 2008). "In vitro, using shrimp gut primary cells (SGP), 2% Aq significantly reduced WSSV infection and the amounts of H2O2 released but had no impact on CAT and SOD expression." (PMID 39857423, 2025). "CAT and SOD1 expression significantly increased in both WL and PC birds, regardless of the source of infection." (PMID 39066292, 2024). "A significant decrease in the CAT and SOD activities was observed 6 h after infection in both the two treatments, and no obvious change was observed in the APX activity." (PMID 37983219, 2023). "The levels of CAT, GPx, CuZn-SOD, and Mn-SOD mRNA expression were significantly downregulated in the infection group as compared to the no infection group." (PMID 35369604, 2022). "Viral particles, purified from the spent medium of either G. duodenalis HP or CAT isolates, were negative contrast stained and analysed by TEM before to carry out the experimental infection." (PMID 34201207, 2021). "While fructans stimulated APX and CAT activity, no significant fructan-induced changes were observed for GPX activity upon pathogen infection." (PMID 32882794, 2020). "Irrespective of the inoculum doses, both CAT and SOD resulted up-regulated during the first four days of infection, and, subsequently, their level in the leaf tissues declined." (PMID 26581656, 2015). "Mtb lacking catalase KatG, was hypersuceptible to H2O2 and attenuated specifically in the chronic phase of infection." (PMID 23326232, 2013). "Uninfected male mice presented greater activity of the enzymes SOD, GPx, and CAT, in addition to higher concentrations of MDA and NO than females did, which confirms that males in the absence of infection suffer from greater oxidative stress in the brain than females do." (PMID 40332798, 2025).
infection (continued). "Interestingly, inoculation with P. halstedii alone did not change SOD, CAT, APX, POX and PPO activities in sunflower seedlings at different stages of infection (3, 9 and 21 dpi) in our study." (PMID 41304631, 2025). "Regarding the enzymatic antioxidant activity, the best response was found in the FCP treatments with 30 min of application, with increases of 25%, 161%, and 450% in ascorbate peroxidase, catalase (CAT), and glutathione reductase (GR) activities, respectively, compared to plants without infection." (PMID 37631184, 2023). "On the other hand, the NGBVI had a positive correlation with CAT, SOD activities and plant weight with the inoculation of B. c-A, before infection with Cmm; however, after infection, it displayed a positive correlation with PAL and CAT activities and a negative correlation with SOD and weight." (PMID 35406912, 2022). "At 24 hpi, the activities of SOD, CAT and LYZ in the intestine were detected to evaluate the effect of DIV1 infection on the nonspecific immunity of M. japonicus, and the activities of α-AMS, LPS and TPS in the intestine were detected to evaluate the digestive function." (PMID 36189245, 2022). "This study reveals that the healing efficacy of G. mangostana crude extract was achieved by reducing the expression of antioxidant genes (CAT, SOD, and GPx) and inflammatory cytokine genes (TGF-β, TNF-α, IFN-γ, and IL-10) to levels similar to those of the no infection group." (PMID 35369604, 2022). "Similarly to MDA, during the first 14 days of infection, catalase activity was not significantly affected in PWN-infected plants, regardless of chitosan elicitation, which remained similar to catalase levels in water-inoculated plants." (PMID 33580134, 2021). "On the other hand, the high accumulation of H2O2 was ascribed to the reduction of CAT and APX activities in non-treated infected plants, suggesting the sensitivity of the studied plants to infection by R. solani and breakdown of main defense strategies, which weaken the resistance of plants." (PMID 34961229, 2021). "However, at 48 h post-infection, upregulated GSH, CAT, and POD could not fully counter H2O2 overaccumulation." (PMID 40559070, 2025). "At 24, 48 and 96 h post-infection, mice were euthanazed (none of the mice succumbed to infection during this time period) and bacteria from the nasopharynx, lungs, blood and brain of each mouse were enumerated by plating on blood agar, and on THY-catalase plates to verify colony phenotype." (PMID 21611130, 2011).